VEGFC (vascular endothelial growth factor C)
Diseases named in the same sentence as VEGFC in open-access papers (continued):
Sharing a sentence is not in itself a finding about the gene and the disease.
pituitary tumor (1 paper, 2022). A benign or malignant neoplasm affecting the pituitary gland. "This suggests that PGF and VEGFC are the main angiogenic growth factors initiating angiogenesis in human pituitary tumors." (PMID 35600354, 2022). "Compared with normal pituitary tissue, genes with the highest to lowest expression levels in pituitary tumor tissue were VEGFC (19.3-fold, p<0.0001), PGF (13.4-fold, p<0.0001), VEGFA (4.2-fold, p<0.0001) and VEGFB (2.2-fold, p=0.002)." (PMID 35600354, 2022). "In addition, we identified PGF and VEGFC as the major angiogenic growth factors regulating angiogenesis in human pituitary tumors." (PMID 35600354, 2022). "Moreover, elevated expression in all types of pituitary tumors was only observed with VEGFC and PGF." (PMID 35600354, 2022). "Pituitary tumors also expressed significantly higher levels of angiogenesis growth factors, including VEGFA (4.2-fold), VEGFB (2.2), VEGFC (19.3), PGF (13.4), ANGPT2 (9.2), PDGFA (2.7), PDGFB (10.5) and TGFB1 (3.8) compared to normal pituitary tissue." (PMID 35600354, 2022). "We next measured primary pituitary tumor production of PGF and VEGFC proteins." (PMID 35600354, 2022). "Furthermore, we identified PGF and VEGFC, but not VEGFA or VEGFB, as the major angiogenic growth factors regulating angiogenesis in human pituitary tumors." (PMID 35600354, 2022). "Angiogenesis in pituitary tumors is regulated mainly by PGF and VEGFC, not VEGFA and VEGFB." (PMID 35600354, 2022).
retinal diseases (1 paper, 2004). "In many instances, this results in a significant reduction of genes in the respective intervals offering a manageable number of candidates for retinal diseases (e.g. the RP29 locus contains 28 SGPs of which 5 are present in the reference retinome including GPM6A, WDR17, FLJ22649, VEGFC, AGA)." (PMID 15283859, 2004).
rosacea (1 paper, 2025). A chronic erythematous skin disorder that affects the face. "Since VEGFC is known to have a selectivity towards lymphatic vessels, targeting of lymphangiogenesis seems to be a possible mechanism to explain the observed positive clinical effect of Artemisinin in rosacea." (PMID 41562711, 2025). "An anti-malarial drug, Artemisinin, decreased the expression of Angiopoietin 2 and VEGFC, but not VEGFA or VEGFB, in a mouse model of rosacea induced by LL37, the proinflammatory form of cathelicidin, and showed a beneficial clinical effect in rosacea patients." (PMID 41562711, 2025).
thymoma (1 paper, 2023). A neoplasm arising from the epithelial cells of the thymus. "B3 thymomas and TC expressed significantly higher levels of both VEGFA and VEGFC compared to A, AB, and B1 thymomas." (PMID 38069386, 2023).
viral myocarditis (1 paper, 2025). Myocarditis that is caused by an infection with a viral agent. "Recently, studies in an animal model of viral myocarditis found that the stimulation of cardiac lymphangiogenesis through adeno-associated viral delivery of VEGFC attenuated inflammation and edema." (PMID 41221452, 2025).
tumor (972 papers, 1999 to 2026). "One of the most well‐known lymphangiogenic factors involved in the process of tumor‐associated lymphangiogenesis is vascular endothelial growth factor C (VEGF‐C)." (PMID 39823128, 2025). "This epigenetic modification upregulates vascular endothelial growth factor C (VEGF-C) expression, inducing tumor-associated lymphangiogenesis." (PMID 41438986, 2025). "Combining HAM with VEGFC facilitates reconstruction of tumor‐associated lymphatic vessels, improving DC migration to TDLNs for optimal T‐cell activation." (PMID 40917034, 2025). "Given the critical roles of these molecules in tumor biology, this study aimed to retrospectively investigate the association of serum VEGFC, VEGFR-3, and IGF1 levels with metastasis and prognosis in a cohort of NPC patients." (PMID 41333209, 2025). "VEGFC has also been shown to recruit tumor-associated macrophages (TAMs) into the mammary gland in mice." (PMID 38218743, 2024). "In particular, the subtype VEGFc has been implicated in promoting BC tumor growth and metastasis, and its expression is also associated with worsened tumor grade in OS83,84." (PMID 38969706, 2024). "Although our results clearly underscore the association between VEGFC and the tumor progression of CSCC, the small number of patients with disease progression or perineural invasion are important limitations." (PMID 38203550, 2023). "In line with transcription regulatory effects in cell models, IHC analysis of tumor samples showed a significant reduction of VEGFC protein levels in JUN-deficient stroma." (PMID 36438487, 2022). "Hypoxia can enhance VEGFC translation, and interstitial pressure increases tumor lymphangiogenesis in order to reduce tumor-associated edema." (PMID 36612017, 2022). "For example, in response to the β-adrenoceptor agonist (βAR) stimulation, tumor-associated macrophages release prostaglandin E2 and stimulate vascular endothelial growth factor C (VEGF-C) expression to increase lymph and blood vessel density." (PMID 36304546, 2022). "The significant upregulation and downregulation of VEGFC expression in tumours were mainly caused by transcriptional regulation." (PMID 35600335, 2022). "The density of CD31+ blood vessels and the expression of vascular endothelial growth factor C (VEGFC) in tumor xenografts were significantly associated with BACH1 levels according to the results of IHC and immunofluorescence (IF) analyses performed in vivo." (PMID 33932125, 2021). "In various human cancers, enhanced expression of VEGFC and higher levels of VEGFC in serum are commonly associated with tumor aggressiveness and lymph-node metastasis." (PMID 32132179, 2020). "The VEGFC-mediated lymphangiogenesis is suggested to be maintained via a paracrine mechanism in which the Flt4 expressed on the lymphatic endothelial cells is activated via its association with tumor cell-derived VEGFC." (PMID 32752094, 2020). "The VEGFC protein functions mainly in the process of lymphangiogenesis but has also been implicated in the promotion of tumor metastasis and growth." (PMID 31766385, 2019). "A host of factors associated with lymphangiogenesis and tumor progression were upregulated following treatment with docetaxel, including VEGFC, TNF-α, IL1, among others." (PMID 29976154, 2018). "The VEGFC-VEGFR3 signaling axis is one of the quintessential drivers of tumor-associated lymphangiogenesis." (PMID 29976154, 2018). "The VEGFC gene encodes one of the most important proteins involved in the activation of tumor angiogenesis and lymphangiogenesis, and its expression is strongly associated with migration and metastasis of many cancers." (PMID 26637806, 2016). "Our results suggest that Enz has a major role in downregulating the u-PAR through Sp1/Sp3 and c-Jun(AP-1), besides HIF1α and VEGFC that are implicated in tumour growth and metastasis, in parallel to upregulating tumour-suppressors relevant for NSCLC." (PMID 20736951, 2010).
tumor (continued). "In addition, a disintegrin and metalloprotease with thrombospondin motifs-3-mediated proteolytic activation of vascular endothelial growth factor-C has been implicated in both developmental and tumor-associated lymphangiogenesis." (PMID 40806273, 2025). "Furthermore, a distinctive feature of HAS is its extensive and abnormal tumor vasculature, which has been linked to the overexpression of vascular endothelial growth factor C (VEGF-C) and angiopoietin-like proteins (ANGPTLs)." (PMID 40655149, 2025). "Furthermore, tumor stromal cells such as macrophages (TAMs) and cancer-associated fibroblasts (CAFs) can secrete VEGFC and other lymphangiogenic factors that contribute to the lymphangiogenic sprout." (PMID 41459512, 2025). "Our analysis implies that VEGF ligands could exert differential effects across cell types: VEGFA may be linked to tumor cell proliferation, while VEGFC appears to support CAF‐mediated tumor protection." (PMID 40843133, 2025). "Paradoxically, FOXO1 may also promote tumourigenesis by directly upregulating the transcription of VEGFC, which is intricately linked with tumour progression and metastasis." (PMID 38899748, 2024). "Blocking the VEGFC/D signaling pathways by administering soluble VEGFR3 encoded by adenovirus or using clodronate liposomes for depletion of tumor-associated macrophages may markedly inhibit lymphangiogenesis in patients with bladder cancer." (PMID 38172098, 2024). "Therefore, metalloproteinases associated with the tumour environment by maturating CTGF liberate VEGFC to stimulate lymphangiogenesis." (PMID 38397987, 2024). "Furthermore, VEGFC has been associated with promoting metastasis in CRC by enhancing tumor cell invasion and migration." (PMID 39328205, 2024). "VEGFC may also stimulate the proliferation and invasion of tumor-associated immune cells like monocytes and macrophages, promoting the growth of KHE." (PMID 38486263, 2024). "For example, tumor-associated macrophages (TAMs) secrete high amounts of VEGFC/D." (PMID 36612017, 2022). "However, VEGFC can also be secreted by cancer cells themselves and directly promote cancer cell migration and invasion, tumor‐associated lymphangiogenesis, and lymphatic metastasis." (PMID 33128283, 2021). "In summary, our demonstration of the important roles of the BRG1/STAT3/VEGFC in tumor-associated lymphangiogenesis might lead to the discovery of novel therapeutic targets in the treatment of cancers with BRG1 loss of function." (PMID 27145366, 2016). "Interestingly, we observed EGF-induced alternative promoter usage of genes that have previously been implicated in tumor progression (e.g., VEGFC, PTK2, IL18 and VAV3) or in cell survival/proliferation (e.g., FBXW7, BID, ABL2)." (PMID 24324612, 2013). "The correlations of NF-κB and Notch1 with lymph node involvement, lymphatic vessel density (LVD), podoplanin, and vascular endothelial growth factor-C (VEGF-C) were further evaluated to determine the association of NF-κB and Notch1 expression with tumor-induced lymphangiogenesis." (PMID 21939555, 2011). "Moreover, decreased VEGFC was shown to correlate with an increased risk of tumour progression." (PMID 33407483, 2021). "BRG1 loss function mutation has been found in several kinds of cancers, and our demonstration of the important role of the BRG1/STAT3/VEGFC in tumor-associated lymphangiogenesis might lead to the discovery of novel therapeutic targets to treat cancer with BRG1 loss of function." (PMID 27145366, 2016). "Finally, a tumor-promoting role for Calreticulin has been shown to be linked to dysregulation of Cortactin expression, and vascular endothelial growth factor C (VEGF-C) contributes to tumor growth and metastasis via Src-miR326-mediated overexpression of Cortactin in ESCC." (PMID 26345720, 2015). "In a mouse model, miR-374b-5p overexpression significantly reduced tumor growth and angiogenesis, and downregulated the lymphangiogenic factor VEGFC." (PMID 41898713, 2026).
tumor (continued). "Further exploration revealed that the downregulation of HMGB1 expression effectively inhibited the NF-κB/p65 and its binding activity to DNA, thereby reducing the expression of vascular endothelial growth factor C (VEGF-C) and impeding tumor angiogenesis." (PMID 40877572, 2025). "VEGFA–KDR interaction was observed between tumor cell subclusters and immune cell types, whereas the VEGFC–KDR interaction signal was exclusive to CAF cells." (PMID 40843133, 2025). "Taken together this suggests CCL21 and VEGFC protein content in tumor-draining PALNs shifts in a predictable manner with mRNA expression of the tumor and with the extent of ablation of the tumor after SA-HFIRE." (PMID 39998766, 2025). "ELISA confirmed that VEGFC production was higher in neutrophils stimulated by oeERβ-CM than in those treated with oeNC-CM, and exceeded levels produced by tumor cells alone." (PMID 40739091, 2025). "CCL21 and VEGFC were measured using ELISA to assess the protein content of downstream PALNs at day 1 and 3, based on previous vascular remodeling in the tumor and TDLNs." (PMID 39998766, 2025). "In this context, taxanes and other chemotherapeutic agents activate the TLR4 signaling pathway in tumor cells, leading to increased VEGFC expression and drug resistance." (PMID 41459512, 2025). "This infiltration subsequently enhances VEGFC secretion by neutrophils, thus promoting tumor lymphangiogenesis and LN metastasis in LUAD cells." (PMID 40739091, 2025). "VEGFA was notably overexpressed in tumor subcluster T2, whereas VEGFC expression was observed in mCAFs and iCAFs, alongside the activation of EMT, PD‐1 signaling, YAP/TAZ signaling, and other fibrosis pathways, except Hippo signaling." (PMID 40843133, 2025). "VEGFA drives tumor proliferation in responders, while VEGFC promotes resistance through TME interaction, FGF signaling, and YAP‐TAZ regulation." (PMID 40843133, 2025). "They found decreased VEGFC immunohistochemistry (IHC) staining and intratumoral lymphatic destruction local to the ablation, as well as disrupted tumor drainage of methylene blue into surrounding lymphatics of the skin." (PMID 39998766, 2025). "Both VEGFA and VEGFC inhibition effectively suppressed tumor growth, suggesting that VEGF signaling complexity hampers the response to ABCP." (PMID 40843133, 2025). "The VEGFC/VEGFR-3 signaling pathway plays a critical role in tumor lymphangiogenesis, facilitating the dissemination of tumor cells to regional lymph nodes and distant sites." (PMID 41333209, 2025). "VEGFA facilitated the proliferation of responder tumor subcluster cells, whereas VEGFC secreted from non‐responder tumor cells interacted with tumor microenvironment cells." (PMID 40843133, 2025). "In the tumor ecosystem, the biological functions of VEGFA and VEGFC are primarily linked to tumor angiogenesis and lymphangiogenesis." (PMID 40843133, 2025). "To probe lymphatic-specific growth factors, we quantified VEGFC expression, a prominent lymphatic growth factor, in the tumor and surrounding mammary fat pad using RT-qPCR." (PMID 39998766, 2025). "Our findings further emphasize the role of VEGFC in cooperating with fibroblastic regulation in tumor development and resistance, highlighting the specific mechanisms by which CAFs interact with VEGF signaling." (PMID 40843133, 2025). "Overall, these co‐expression networks elucidated the distinct roles of the two VEGF ligands: VEGFA contributes to tumor proliferation, whereas VEGFC potentiates desmoplasia and anticancer immunity." (PMID 40843133, 2025). "While VEGFA, expressed by all tumor cell types, facilitated tumor cell proliferation, the VEGFC–KDR signal was restricted to interactions between specific T1 tumor cells and other CAF subtypes, promoting the development of meCAFs." (PMID 40843133, 2025).
tumor (continued). "Increasing evidence has revealed additional functions of VEGFC beyond the lymphatic system, such as regulating macrophages 81, NK cells 82, and platelet generation by megakaryocytes 83, which can affect tumor immunity in various ways." (PMID 40083688, 2025). "Taken together, these findings indicated that VEGFA in tumor cells appears to maintain tumor cell proliferation, whereas VEGFC in TME cells protects tumor cells via mCAF development with FGF signaling activation or YAP‐TAZ regulation." (PMID 40843133, 2025). "Vascular endothelial growth factor-C (VEGF-C) participates in the regulation of tumor angiogenesis and lymphangiogenesis and is considered to be a multifaceted factor." (PMID 40299334, 2025). "VEGFC expression promotes the infiltration of naïve and regulatory T cells, a response that has been used to induce enrichment of tumor-infiltrating naïve T cell in cancer immunotherapies." (PMID 39880866, 2025). "VEGFC has been shown to stimulate tumor cell growth and migration, as well as enhance neovascularization." (PMID 38486263, 2024). "In CRC, increased lymphangiogenesis facilitated by VEGFC promotes tumor cell dissemination through lymphatic vessels, leading to lymph node metastasis." (PMID 39328205, 2024). "Meanwhile, in the mid-term (2012–2017), “vascular endothelial growth factor-c,” “lymphangiogenesis,” and “vegf-d promotes” emerged, and in the later stage (from 2018 to the present), “tumor microenvironment,” “metastasis,” and “blood vessels” surfaced." (PMID 38549934, 2024). "One of the most important drivers of lymphatic development is VEGFC, which exerts a pro- or anti-tumour role depending on the tumour stage." (PMID 38397987, 2024). "The genes FLT1, VEGFC, VWF, and VEGFD are closely linked to angiogenesis and vascular function, playing important roles in tumor angiogenesis." (PMID 38486263, 2024). "In this context, anti-VEGFC antibodies also have important anti-tumour activity as they target both tumour cells and the lymphatic network." (PMID 38397987, 2024). "They revealed that OGCs in the tumor environment promoted tumor growth and lymphangiogenesis by secreting vascular endothelial growth factor-C." (PMID 38643211, 2024). "These enlarged vessels have been visualized via intravital microscopy and fluorescence photobleaching in a mouse tumor model with VEGFC overexpression." (PMID 38218743, 2024). "Yu Han Huang etc. proved that IL6 induces vascular endothelial growth factor-C expression in lymphatic endothelial cells, as the effort to understand the underlying mechanism may help in developing novel therapeutic strategies to reduce lymphangiogenesis and tumor metastasis." (PMID 38893732, 2024). "Vascular endothelial growth factor C (VEGFC) contributes to tumor progression by affecting tumor cells directly or by regulating lymphangiogenesis and immune responses." (PMID 38486263, 2024). "VEGFC treatment also increased the priming and clonal expansion of tumor antigen-specific T cells in extracranial lymph nodes." (PMID 38648267, 2024). "The expression of vascular endothelial growth factor-C (VEGF-C) in iCCA cells has been reported to be positively correlated with lymphatic invasion and tumor progression." (PMID 38057358, 2024). "In prostate cancer, COX2 correlates with VEGFC expression, tumor lymphangiogenesis, and lymphatic metastasis." (PMID 38218743, 2024). "HIF-1α, VEGFA, and VEGFC have been reported to act as factors that contribute to tumour angiogenesis." (PMID 38035445, 2024). "A series of studies have revealed that LPA promoted lymphangiogenesis by increasing the expression of the important prolymphangiogenic factor VEGFC in targeted cells such as tumor cells and endothelial cells." (PMID 38172098, 2024).